IL6 (interleukin 6)
Diseases named in the same sentence as IL6 in open-access papers (continued):
Sharing a sentence is not in itself a finding about the gene and the disease.
chronic obstructive pulmonary disease (168 papers, 2006 to 2026). A chronic and progressive lung disorder characterized by the loss of elasticity of the bronchial tree and the air sacs, destruction of the air sacs wall, thickening of the bronchial wall, and mucous accumulation in the bronchial tree. "Canonical pathway analysis predicted that the upregulated genes were associated with airway pathology in chronic obstructive pulmonary disease, granulocyte adhesion and diapedesis and IL‐17 and IL‐6 signalling." (PMID 38375330, 2024). "IL-6 is highly elevated cytokine in mouse model of chronic obstructive pulmonary disease (COPD)-like inflammation and has been implicated in inflammatory responses in human COPD." (PMID 24204835, 2013). "Elevated circulating levels of C-reactive protein (CRP), interleukin (IL)-6 and fibrinogen (FG) have been repeatedly associated with many adverse outcomes in patients with chronic obstructive pulmonary disease (COPD)." (PMID 19272152, 2009). "On the other hand, another study demonstrated that the concentrations of vWF were unrelated to postoperative AF, while intracardiac levels of IL-6 were associated with AF, emphasizing the heterogeneity and complexity of the inflammatory system in the development of cardiac arrhythmias." (PMID 41010936, 2025). "IL-6 is a key inflammatory marker in many mouse models, including the age-related hearing loss mouse model and the COPD (chronic obstructive pulmonary disease)-like inflammatory mouse model." (PMID 38393014, 2024). "IL-6 trans-signaling was strongly associated with NET formation induced by Haemophilus influenzae in chronic obstructive pulmonary disease (COPD) patients." (PMID 36532016, 2022). "Compounds 58 and 145–149 had inhibitory effects on the IL-6 expression and promoting effects on the IL-10 expression in the serum of rats induced by chronic obstructive pulmonary disease (COPD) caused by cigarette smoking." (PMID 33260848, 2020). "Additionally, several reports indicate that IL-6 primarily contributes to increments in respiratory system resistance, and its pathogenic role in several respiratory disorders, such as asthma and chronic obstructive pulmonary disease (COPD), has been described." (PMID 32655577, 2020). "They produce typical neutrophil-recruiting cytokines like IL-6 and IL-8, thereby participating in the excessive accumulation of neutrophils in asthma and chronic obstructive pulmonary disease (COPD)." (PMID 40486514, 2025). "Dysbiosis can lead to chronic inflammation, with elevated levels of pro-inflammatory cytokines, such as IL-6, TNF-α, and IL-1β, being linked to an increased risk of cardiac arrhythmias." (PMID 38892965, 2024). "High-fructose diets cause heart–gut axis disorders that promote cardiac arrhythmia through potentiating proinflammatory mediator, such as tumor necrosis factor alpha (TNF-α), nuclear factor-κB (NF-κB), and interleukin 6 (IL-6)." (PMID 37367916, 2023). "This IL-6 trans-signaling has similarly been observed recently in chronic obstructive pulmonary disease (COPD) in a subset of patients colonized with increased proteobacteria, particularly Haemophilus genus, where sIL-6R is correlated with markers of NETosis." (PMID 37180449, 2023). "We recently demonstrated that peroxisomal dysfunction in Drosophila liver induced cardiac arrhythmia through the production of inflammatory cytokine upd3/IL-6." (PMID 35204075, 2022). "IL-6 has been implicated in the pathogenesis of many inflammatory disorders of the lung, including IPF, ARDS, and chronic obstructive pulmonary disease." (PMID 35355866, 2022).
chronic obstructive pulmonary disease (continued). "A study in rats with EPOC also showed an increase in 8-isoprostanes and IL-6 in lung lysates associated with ACE2 overexpression and another study demonstrated an increase in urinary 8-isoprostanes levels in patients with chronic obstructive pulmonary disease." (PMID 35326383, 2022). "Treatment with HET has been shown to decrease serum IL-6 in patients with chronic obstructive pulmonary disease." (PMID 36034871, 2022). "IQR: Interquartile range; SD: Standard deviation; BMI: Body mass index; COPD: Chronic obstructive pulmonary disease; IL-6; Interleukin-6; ICU: Intensive care unit." (PMID 35959182, 2022). "For example, decreased expression of the ARE binding protein AUF-1 in chronic obstructive pulmonary disease (COPD) patient samples leads to stabilization of IL-6, CCL2, CCL1 and CXCL8 mRNA." (PMID 33806254, 2021). "It has been reported that chronic obstructive pulmonary disease (COPD) patients have high levels of IL-6 and nitric oxide (NO), and GTS-21 treatment suppresses the IL-6 and NO levels in plasma by modulating the function of PBMCs." (PMID 33936095, 2021). "Recent studies established that IL6 substantially contribute in the diagnosed of systemic inflammation for the patients suffering from lung diseases such as chronic obstructive pulmonary disease (COPD)." (PMID 32802897, 2020). "Elevated blood levels of pro-inflammatory markers, such as CRP and IL-6, are found in patients with chronic obstructive pulmonary disease (COPD)." (PMID 31151190, 2019). "The concentration of CA125 was positively related to age, hospitalization for HF and history of atrial fibrillation and chronic obstructive pulmonary disease, levels of NT-proBNP, IL-6, hs-CRP and triglycerides." (PMID 31058877, 2019). "One of the specific functions of IL6, which has recently been discovered, is its prime role in the inflammatory processes of lung disease, particularly chronic obstructive pulmonary diseases (COPD), bronchiolitis and asthma." (PMID 25031491, 2014). "Even more, there is evidence of a substantial involvement of the tumor necrosis factor-alpha system in the pathophysiology of cardiac arrhythmia, while the role of Interleukin 6 remains inconclusive." (PMID 24770373, 2014). "The IL-6 levels frequently increase in patients suffering with several pulmonary diseases, including infectious pneumonia, interstitial pneumonia and chronic obstructive pulmonary disease." (PMID 19943923, 2009). "Previous studies demonstrated that Haemophilus influenzae leads to airway inflammation deterioration, induced by cigarette smoke exposure in COPD (chronic obstructive pulmonary disease) mice, and the production of the pro-inflammatory mediators interleukin-6 (IL-6) and IL-1β." (PMID 35158583, 2022). "In addition, the elevated gene expression of CCR5 was found in intermediate monocytes from patients with chronic obstructive pulmonary disease as a result of high circulating IL-6 and sIL-6R levels." (PMID 35216350, 2022). "For example, a study using a mouse model of chronic obstructive pulmonary disease found that memantine could inhibit the expression of IL-6, TNF-α, and interferon-γ, thereby reducing pulmonary inflammation." (PMID 33174867, 2020). "Furthermore, there is evidence from previous studies that interleukin 6 (IL-6) plays a major in role in the pathophysiology of cardiac arrhythmia." (PMID 24770373, 2014). "In this study, we investigated the diagnostic utility of a plasma interleukin panel comprising IL-6, IL-10, IL-8, and IL-1RA to distinguish early-stage NSCLC from healthy individuals and patients with chronic obstructive pulmonary disease (COPD)." (PMID 41303495, 2025). "Owing to their pivotal roles in inflammation, IL-1β and IL-6 have been proposed as biomarkers of lung injury and airway inflammation, particularly in diseases such as chronic obstructive pulmonary disease (COPD), ALI and ARDS." (PMID 39949769, 2025).
chronic obstructive pulmonary disease (continued). "Foamy macrophages contribute significantly to the chronic inflammatory milieu of chronic obstructive pulmonary disease (COPD) by releasing pro-inflammatory cytokines such as IL-6, TNF-α, IL-1α, and IL-1β." (PMID 41009372, 2025). "The present study investigated serum interleukin-6 (IL-6) and adipolin levels in chronic obstructive pulmonary disease (COPD) patients." (PMID 36136851, 2022). "This study aims to explore the correlation between high-sensitivity C-reactive protein (hs-CRP), interleukin-6 (IL-6), interleukin-10 (IL-10), endothelin-1 (ET-1), and chronic obstructive pulmonary disease combined with pulmonary hypertension (COPD-PH)." (PMID 35186226, 2022). "An increased level of IL-6 was reported in chronic obstructive pulmonary disease (COPD) and is thought to be an indicator of poor clinical outcome in COPD patients." (PMID 34829902, 2021). "Chronic obstructive pulmonary disease (COPD) is a complex condition in which systemic inflammation plays a role in extrapulmonary manifestations, including cardiovascular diseases: interleukin (IL)-6 has a role in both COPD and atherogenesis." (PMID 34768536, 2021). "The present study aimed to examine serum FABP-4 and interleukin (IL)-6 levels in patients with stable and acute exacerbation of chronic obstructive pulmonary disease (COPD) and the correlation of these markers with airflow limitation." (PMID 31905499, 2020). "For example, patients with chronic obstructive pulmonary disease (COPD) with increased levels of Il-6, Il-8, TNF-α demonstrated decreased levels of SQSTM1/p62 in PBMCs." (PMID 30633777, 2019). "Increased IL-6 levels in induced sputum have been found in patients with severe-very severe Chronic Obstructive Pulmonary Disease (COPD) relative to mild-moderate COPD patients." (PMID 20205953, 2010). "The most recent finding examined the preventative effects of crocin supplementation on blood levels of IL-6 and TNF-α, exercise ability, and pulmonary function tests (PFT) in Chronic obstructive pulmonary disease (COPD) patients." (PMID 40154100, 2025). "In a double-blind clinical trial involving patients with Chronic Obstructive Pulmonary Disease (COPD), CLA supplementation was shown to significantly decrease serum IL-6 levels, thus improving overall health." (PMID 40284258, 2025). "Pro-inflammatory mediators such as cytokines (IL-1, IL-6, TNF, etc.), ROS, and proteolytic enzymes are implicated in cell and tissue damages associated with many chronic inflammatory diseases, including chronic obstructive pulmonary disease (COPD)." (PMID 38675465, 2024). "In chronic obstructive pulmonary disease (COPD), miR-let-7 137 can regulate airway remodeling in the lungs by reducing IL-6 expression through direct targeting of IL-6 mRNA." (PMID 39113708, 2024). "It has also been found that 45 min of H2 gas inhalation reduced airway and pulmonary inflammation in chronic obstructive pulmonary disease (COPD) and asthma patients by reducing MCP-1, IL-6, and IL-4 levels." (PMID 37509530, 2023). "Another study sought to determine how high-dose vitamin D (300,000 IU) supplementation affected systemic inflammatory biomarkers (IL-6, IL-8, CRP) in patients with chronic obstructive pulmonary disease experiencing acute exacerbation." (PMID 37375645, 2023). "We showed that the production of upd3/IL-6 activated the cardiac JAK-STAT signaling pathway and induced cardiac arrhythmia." (PMID 35204075, 2022). "Soluble uric acid exerts an inflammation‐stimulatory effect and induced the production of tumor necrosis factor α (TNFα), interleukin (IL)‐6, and IL‐1β,25 it also involved in the lung injury, COPD (chronic obstructive pulmonary disease), and EP (eosinophilic pneumonia)." (PMID 34655117, 2021). "Similar patterns, including trends towards dose-dependent increases in IL-6 and also IL-1RN and FGF-7 were observed in mRNA levels from hMSCs exposed to two separate CF and one chronic obstructive pulmonary disease (COPD) BALF samples." (PMID 31553626, 2019).
chronic obstructive pulmonary disease (continued). "Increased concentrations of fibrinogen are observed in stable chronic obstructive pulmonary disease (COPD), and during the acute stage of the disease, it is accompanied by an upswing in serum levels of IL-6." (PMID 31151190, 2019). "Inhibition of IL-6 (or IL-6R) may be a therapy for asthma, chronic obstructive pulmonary diseases (COPD), and other lung diseases." (PMID 29674943, 2018). "IL6 was found to be increased in lSSc-PAH patients on the cytokine array, and IL6 is also associated with PAH in the context of chronic obstructive pulmonary disease (COPD)." (PMID 20808962, 2010). "on patients with moderate chronic obstructive pulmonary disease, using an amplitude of 2 mm and a frequency of 30–40 Hz, showed that there was no significant improvement in IL-6 levels in the intervention group." (PMID 41293158, 2025). "However, the association between psychosomatic syndrome and pro-inflammatory factors such as IL-6, CRP, and PCT in the peripheral blood of acute exacerbation of chronic obstructive pulmonary disease (AECOPD) patients is still unclear." (PMID 40708589, 2025). "Furthermore, another study on patients with chronic obstructive pulmonary disease by Rubing Mo and collaborators found that LPS induces lncRNA GAS5 expression and release of IL-2, IL-6, IL-10, and TNF-α." (PMID 37047453, 2023). "In addition, Wnt5a is reported to be increased in experimental and human chronic obstructive pulmonary disease (COPD) and to induce production of inflammatory cytokines such as IL-6 and TNF-α." (PMID 38062395, 2023). "While sulforaphane (30 mg/d for 4 weeks) reduced exercise-induced IL-6 levels in young healthy men, sulforaphane (up to 26.6 mg/d for 4 weeks) did not change inflammatory markers, including IL-6 levels, in patients with chronic obstructive pulmonary disease." (PMID 36525453, 2022). "Furthermore, patients with chronic obstructive pulmonary disease (COPD) had higher plasma levels of ICAM-1 and IL-6 compared to healthy subjects." (PMID 29329563, 2018). "It was confirmed through in vitro and in vivo experiments that ergosterol reduces ROS, IL-6, and TNF-α, demonstrating anti-inflammatory and anti-senescence properties in managing chronic obstructive pulmonary disease (COPD)." (PMID 40559397, 2025). "MgIG (0.80 mg/kg/day) significantly reduced the concentration of IL-6 and TNF-α at the lung and serum levels in rats with experimentally induced chronic obstructive pulmonary disease COPD." (PMID 41597294, 2025). "The ethanol extract of the tuber of A. orientale Juzepzuk (EEAO) relieved the pathological features of chronic obstructive pulmonary disease (COPD) by suppressing lung emphysema and autophagy and inducing TNF-α, IL-6, and TGF-β in a mouse model." (PMID 38166725, 2024). "RSV also improved lung histological damage and decreased pro-inflammatory cytokines (IL-6, IL-17, TNF-α, and TGF-β) in cigarette smoke chronic obstructive pulmonary disease (COPD) animals." (PMID 37229273, 2023). "In chronic obstructive pulmonary disease (COPD), activation of ERK produces pro-inflammatory cytokines, such as TNF-α, IL-1β, IL-6 and IL-8." (PMID 35889800, 2022). "A total of 379 targets related to BHC and 7391 targets related to COPD were obtained, including 313 potential targets of BHC in treating chronic obstructive pulmonary disease, with JUN, AKT1, TNF, IL6, EGFR, MAPK1, and MAPK14 as the core targets." (PMID 36523421, 2022). "Interleukin (IL)-1α, IL-1β, IL-6, IL-8 and tumor necrosis factor (TNF)α contribute to inflammation in chronic obstructive pulmonary disease (COPD)." (PMID 33266187, 2020). "Nesfatin-1 levels in plasma from chronic obstructive pulmonary disease (COPD) patients are correlated with plasma levels of interleukin-6 (IL-6), interleukin-8 (IL-8), and tumor necrosis factor-α (TNF-α), implying that nesfatin-1 acts as a novel inflammatory factor in COPD patients." (PMID 36008865, 2022).
co-infection (167 papers, 2006 to 2026). "EBV coinfection intensified this phenotype, being associated with elevated levels of IL-6, IL-10, IL-15, TNF-α, and sCD40L, and with greater loss of memory cell subpopulations." (PMID 41929504, 2026). "In our study, Welch’s test was used to determine the significance of differences in the range of the analyzed proinflammatory cytokines, TNF-α, IL-1β and IL-6, associated with the three tested atypical pathogens and their co-infections." (PMID 40647668, 2025). "MHV co‐infection in ZBP1‐deficient mice synergistically amplified Il6 and Tnf expression, whereas Il1b, Cxcl1, and Cxcl5 levels remained refractory to further elevation." (PMID 40810650, 2025). "To investigate the innate immune response caused by IBDV and FAdV co-infection, we examined the mRNA expression levels of IL-6, IL-1β, IFN-α, and IFN-γ in the spleen because it is the principal organ of systemic immunity." (PMID 33926543, 2021). "Peters and Noverr demonstrated that co-infection was associated with an increased inflammatory response characterized by an up to 100-fold increase in inflammatory cytokines (e.g. IL-6) and neutrophil influx." (PMID 32068530, 2020). "IL-6 has been shown to decrease susceptibility to co-infection by reducing cells death following IAV-triggered death in the lungs." (PMID 32038632, 2019). "Initially, we observed loss of IL-6 during co-infection resulted in higher levels of IFN-γ in the lung homogenate and BALF of mice." (PMID 32038632, 2019). "Interestingly, the risk of coinfection was also greater in patients with an IL-6 concentration < 10 pg/ml (OR = 1.69, 95%CI = 0.97–2.94)." (PMID 38616284, 2024). "Notably, IL-6 is one of the most highly induced cytokines during viral-bacterial coinfection and is associated with worsened disease outcome (23, –, 25)." (PMID 37772820, 2023). "In previous reports by other authors, the increase in IL-6 levels was often associated with poor functional outcomes, but it was not clear whether this was an independent effect or related to a co-infection." (PMID 36142524, 2022). "Co-infection was associated with increased IL-6 (P = 0.043) and IL-12B (P = 0.017) expression." (PMID 33819170, 2021). "In regard to the immunity of individual patients, a previous study showed that co-infection has been associated with a strong activation of acute phase response, such as Interleukin 6 (IL-6), Tumor necrosis factor-α (TNF-α), and IL1-β and also Th1 cytokines (IFN-γ and IL-12)." (PMID 31522680, 2019). "Furthermore, our ROC curve analyses of inflammatory biomarkers—particularly the combined use of IL-6 and IL-10—provided novel and valuable diagnostic insights, significantly improving the predictive accuracy for detecting severe cases complicated by co-infections." (PMID 40487016, 2025). "In addition, compared with PbANKA-mono-infection, co-infection resulted in elevated Gal-1, Gal-3, M1 markers (IL-1β and iNOS), and IL-6 in the peritoneal macrophages, which may be associated with enhanced liver immunopathology during the co-infection." (PMID 32883347, 2020). "A separate analysis of 127 people with HIV/HCV coinfection who received a 12-week course of ledipasvir/sofosbuvir (99 who achieved cure) evaluated the impact of HCV cure on serum IL-6 and soluble tumor necrosis factor receptor I." (PMID 41018711, 2025). "Protein-protein interaction network analysis further delineated pathogen-specific hubs: inflammatory mediators (CXCL8, CCL20, IL6) in the E group, molecular chaperones (CCT5, RUVBL1/2) in the S group, and a distinctive IL6-FBL-centered network in co-infection." (PMID 40771952, 2025). "Consistent with our results, in vitro co-infection of human PBMC with DENV and CHIKV significantly suppressed CHIKV replication and increased secretion of IL-6 and TNF-α, two proinflammatory cytokines highly associated with dengue pathogenesis." (PMID 40920827, 2025).